PPP1R12A (protein phosphatase 1 regulatory subunit 12A)
Description:
Key regulator of protein phosphatase 1C (PPP1C). Mediates binding to myosin. As part of the PPP1C complex, involved in dephosphorylation of PLK1. Capable of inhibiting HIF1AN-dependent suppression of HIF1A activity.
Synonyms: MBS; MYPT1; M130; GUBS
Tractability: Antibody: its Gene Ontology location is reachable by antibodies, with high confidence. PROTAC: ubiquitination databases record sites on it; its protein half-life has been measured.
Target class: Protein phosphatase regulatory subunit; Phosphatase; Enzyme; Protein Phosphatase
Gene: Protein-coding gene on chromosome 12 (79,773,563 to 79,935,460, reverse strand). Ensembl gene ENSG00000058272.
Subcellular location: Cytoplasm; Cytoplasm, cytoskeleton, stress fiber
Subcellular location (Human Protein Atlas): Actin filaments; Cytosol; Nucleoli; Plasma membrane
Pathways (Reactome):
Signal Transduction: RHO GTPases Activate ROCKs; RHO GTPases activate CIT; RHO GTPases activate PAKs; RHO GTPases activate PKNs
Cell Cycle: Regulation of PLK1 Activity at G2/M Transition
Gene Ontology:
Molecular function: 14-3-3 protein binding; enzyme inhibitor activity; phosphatase regulator activity; protein binding; protein kinase binding; myosin phosphatase regulator activity
Biological process: centrosome cycle; mitotic cell cycle; negative regulation of catalytic activity; positive regulation of transcription by RNA polymerase II; protein dephosphorylation; regulation of cell adhesion; regulation of establishment of endothelial barrier; neuron projection morphogenesis; signal transduction
Cellular component: actin cytoskeleton; centrosome; contractile muscle fiber; cytoplasm; cytosol; focal adhesion; kinetochore; PTW/PP1 phosphatase complex; A band; nucleoplasm; Z disc; stress fiber
Genetic constraint (gnomAD): Loss-of-function variants: 7 observed, 83.12 expected, observed/expected ratio (o/e) 0.0842, 90% interval 0.047 to 0.16. The upper end of that interval is the gene's LOEUF score, 0.16, which puts it in group 1 of 6, group 1 being the genes least tolerant of losing a copy. Missense variants: 718 observed, 950.52 expected, observed/expected ratio (o/e) 0.76, 90% interval 0.71 to 0.8. Synonymous variants: 346 observed, 340.95 expected, observed/expected ratio (o/e) 1.01, 90% interval 0.93 to 1.11.
Gene-disease validity (ClinGen):
ClinGen rates the evidence that PPP1R12A causes each of these diseases.
genitourinary and/or brain malformation syndrome (autosomal dominant): Strong.
Homologues: Orthologues: chimpanzee PPP1R12A (99% identical), macaque PPP1R12A (99% identical), guinea pig PPP1R12A (97% identical), dog PPP1R12A (97% identical), rabbit PPP1R12A (96% identical), rat Ppp1r12a (94% identical), mouse Ppp1r12a (93% identical), pig PPP1R12A (93% identical), tropical clawed frog ppp1r12a (78% identical), zebrafish ppp1r12a (73% identical). Paralogues in human: PPP1R12B (48% identical), PPP1R12C (34% identical), PPP1R27 (6% identical).